DYRK1A (dual specificity tyrosine phosphorylation regulated kinase 1A)
Diseases named in the same sentence as DYRK1A in open-access papers (continued):
Sharing a sentence is not in itself a finding about the gene and the disease.
Down syndrome (continued). "DYRK1A is localized in the Down syndrome (DS) critical region of chromosome 21 that has been linked to the development of DS phenotypes when triplicated." (PMID 23665168, 2013). "The Dyrk1a gene has been implicated in Down Syndrome (DS) and the expression level of Dyrk1a is increased in DS patients and Ts65Dn mice, a mouse model of Down syndrome." (PMID 22876196, 2012). "In Down syndrome (DS), chromosome 21 trisomy gives patients three copies of a critical region that includes the Mnb/Dyrk1a; trisomy of this region is associated with anomalies of both the nervous and endocrine systems." (PMID 22876196, 2012). "We and others have implicated DYRK1A in the phosphorylation of tau protein on multiple sites associated with tau pathology in Down Syndrome and in Alzheimer's disease (AD)." (PMID 21573099, 2011). "Overexpression of DYRK1A has been proposed to be a significant contributor to the underlying neurodevelopmental abnormalities associated with Down syndrome." (PMID 21573099, 2011). "The gene encoding DYRK1A is located within the Down Syndrome critical region (DSCR) on chromosome 21." (PMID 20067632, 2010). "One such region, DCR-1, contains 19 genes, one of which — DYRK1A [Dual specificity Tyrosine(Y) Regulated Kinase 1A] — is closely associated with Down syndrome phenotypes." (PMID 19242551, 2009). "As increased expression of DYRK1A and low plasma homocysteine level have been associated with Down syndrome, we aimed to analyze the effect of its over-expression on homocysteine metabolism in mice." (PMID 19844572, 2009). "DYRK1A is of interest because it has been linked to Down's syndrome and is expressed in the developing and mature brain." (PMID 19583853, 2009). "In humans, DYRK1A has been proposed to be involved in the neurodevelopmental alterations associated with Down syndrome." (PMID 17205196, 2006). "Hence, DYRK1A-mediated (hyper)phosphorylation of tau is more accentuated in patients with Down syndrome, thus putting them at a higher risk of developing tau pathology and AD." (PMID 41513640, 2026). "In addition, DYRK1A is located on human chromosome 21, and its overexpression has been implicated in multiple diseases, most notably Down syndrome and AD." (PMID 41306975, 2025). "Looking ahead, this work sets the stage for expanded investigations into the mechanisms of flavonol-mediated DYRK1A inhibition and their therapeutic potential in preclinical models of DYRK1A-associated diseases, such as Alzheimer’s disease, Down syndrome and cancer." (PMID 40723805, 2025). "The human Dyrk1A gene is located on chromosome 21 in the Down syndrome critical region and is associated with Down syndrome and neurodegenerative diseases, whereas the human Dyrk1B gene is located on chromosome 19q13.2, a region often amplified in ovarian and pancreatic cancer." (PMID 38675189, 2024). "Both overexpression and insufficiency of this gene are associated with many recognizable disorders, including Down syndrome and DYRK1A-related intellectual disability syndrome which is characterized by distinct physical features with microcephaly and global developmental delay." (PMID 39109359, 2024). "The human dual specificity tyrosine phosphorylation regulated kinase 1A (DYRK1A) is implicated in the pathology of Down syndrome, microcephaly, and cancer; however the exact mechanism through which it functions is unknown." (PMID 39271109, 2024). "Down syndrome is a genetic-based disorder that results from the triplication of chromosome 21, leading to an overexpression of many triplicated genes, including the gene encoding Dual-Specificity Tyrosine Phosphorylation-Regulated Kinase 1A (DYRK1A)." (PMID 39114642, 2024).
Down syndrome (continued). "DYRK1A mutations have been linked to multiple neurological disorders including Down syndrome, intellectual development disorder autosomal dominant 7 (MRD7), dementia, Alzheimer's disease, fronto-temporal degeneration, Huntington's disease, and Parkinson's disease." (PMID 39109359, 2024). "Furthermore, DYRK1A is suspected to be involved in some of the pathways that lead to an increased cancer risk for individuals with Down’s Syndrome." (PMID 35989379, 2022). "This DYRK1A overexpression has been linked to the cognitive deficits associated with Down Syndrome." (PMID 34445786, 2021). "Thus, while physiological levels of DYRK1A are critical for brain development, deregulation of DYRK1A expression is associated with developmental and cognitive deficits in Down Syndrome, Autism Spectrum Disorder, Alzheimer’s and Parkinson’s Disease." (PMID 33924599, 2021). "Moreover, hyperphosphorylation caused by DYRK1A overexpression has been implicated in many pathogenetic changes attributed to brain diseases, particularly in Down Syndrome and Alzheimer’s Disease." (PMID 34445786, 2021). "Overexpression of Dyrk1a causes a major deficit in the level of serotonin in the brain, as well as deficit of dopamine and adrenaline neurotransmitters in a transgenic mouse model for Down syndrome." (PMID 34290629, 2021). "DYRK1A has been linked to the memory and learning deficits associated with Down syndrome." (PMID 31995614, 2020). "Interestingly, DYRK1A has been associated with acute lymphoblastic leukaemia (ALL) in children with Down syndrome (DS), because it is located on chromosome 21 and overexpressed as part of the trisomy that characterizes this disease." (PMID 32066817, 2020). "On the one hand, its overexpression in trisomy 21 has been linked to certain pathological traits of Down syndrome, while on the other, inactivating mutations in just one allele are responsible for a distinct yet rare clinical syndrome, DYRK1A haploinsufficiency." (PMID 30979931, 2019). "Dual-specificity tyrosine-phosphorylation-regulated kinase 1A (DYRK1A), encoded by a gene localized in the Down syndrome critical region of chromosome 21, is a serine/threonine protein kinase which contributes to various biological processes in the embryonic and adult central nervous systems." (PMID 30885273, 2019). "Increased DYRK1A activity is associated with Down syndrome (DS) and Alzheimer’s disease (AD)." (PMID 29364148, 2018). "Overexpression of Dual‐specificity tyrosine‐phosphorylated regulated kinase 1A (DYRK1A), located on human chromosome 21, may alter molecular processes linked to developmental deficits in Down syndrome (DS)." (PMID 28944229, 2017). "In addition to the co-localization with NFTs and EAAT1, SEPT4 has been linked to PD and Down syndrome through interaction with parkin and DYRK1A (dual-specificity tyrosine phosphorylation-regulated kinase 1A)." (PMID 25888325, 2015). "Moreover, radial glial progenitors in the Ts65Dn mouse model of Down syndrome have less Cyclin D1, and Dyrk1a is the triplicated gene that causes both early cortical neurogenic defects and decreased nuclear Cyclin D1 levels in this model." (PMID 26137553, 2015). "In particular, Dyrk1A is discussed to be causally involved in the development of Alzheimer–like neurodegenerative diseases in Down Syndrome patients, where the kinase is 1.5-fold overexpressed due to its location in the so-called Down Syndrome Critical Region on chromosome 21." (PMID 24676346, 2014). "Of these, DYRK1A has been characterized most extensively, and it is associated with Down Syndrome." (PMID 20865124, 2010). "In humans and mice, DYRK1A has been linked to the neurite spine morphogenesis, and it has been suggested that the neurite spine phenotype may contribute to intellectual disability in Down syndrome." (PMID 39436397, 2024). "Notably, DYRK1A is also encoded on chromosome 21 and expressed 1.5 fold in Down syndrome patients." (PMID 38902238, 2024).
Down syndrome (continued). "It is unknown whether Dyrk1a mutations have a direct impact on ciliogenesis in the respiratory tract of patients with Down syndrome; however, cilia formation is disrupted in trisomy 21 cells derived from patients with Down syndrome." (PMID 34787650, 2022). "Dyrk1A activity is responsible for neurological defects in Down syndrome and acts as a priming kinase for Alzheimer's disease-associated proteins Tau and APP." (PMID 42131436, 2026). "DYRK1A gene is located on chromosome 21 and is overexpressed in Down syndrome due to an additional copy of this chromosome." (PMID 41513640, 2026). "The DYRK1A enzyme is a pivotal contributor to frequent and severe episodes of otitis media in Down syndrome, positioning it as a promising target for therapeutic interventions." (PMID 39840732, 2025). "We previously showed that DYRK1A interacts with the REST/NRSF-SWI/SNF chromatin remodeling complex to deregulate gene clusters involved in the neuronal phenotypic traits of Down syndrome." (PMID 40003558, 2025). "The overexpression of HSA21 genes like DSCAM, RCAN1, and DYRK1A in Down syndrome disrupts calcium homeostasis, primarily by suppressing the calcineurin pathway." (PMID 40964031, 2025). "Specifically, DYRK1A resides in the Down syndrome critical region (DSCR) and contributes to various phenotypes of Down syndrome, including cognitive disability and memory and learning impairments." (PMID 41306975, 2025). "DYRK1A is involved in the progression of several diseases, such as diabetes, Down syndrome, Alzheimer’s disease, and cancer." (PMID 40699724, 2025). "Future efforts should delineate the feasibility and relevance of pharmacologically targeting DYRK1A signaling as a therapeutic strategy for correcting these inflammatory disorders in individuals with Down syndrome." (PMID 40519271, 2025). "For example, genetic DYRK1A overexpression (e.g., in DYRK1A transgenic mice or Down syndrome patients) increases total tau levels, tau hyperphosphorylation, and NFT formation." (PMID 41306975, 2025). "Now, in eLife, Steve Brown, Hilda Tateossian and colleagues have identified a gene known as DYRK1A as a critical driver of otitis media in Down syndrome." (PMID 39840732, 2025). "DYRK1A is located on chromosome 21q22.13, within the Down syndrome critical region, and exerts its effects in a dosage-sensitive manner." (PMID 40405340, 2025). "Specifically, DYRK1A expression is increased in the brains of patients with AD or Down syndrome or in DYRK1A-overexpressing transgenic mice (DYRK1A Tg mice) compared to healthy/WT controls." (PMID 41306975, 2025). "Through LAMP2A knockout in NPC, we identified a significant upregulation of DYRK1A, a core mediator of premature senescence in Down syndrome." (PMID 40506462, 2025). "DYRK1A plays a crucial role in cellular growth, development, and differentiation and is particularly well-known for its involvement in neurodevelopment and Down syndrome." (PMID 40723805, 2025). "The dose dependent inhibition of DYRK1A is an attractive target for the management of Down syndrome related neurological effects." (PMID 40356974, 2025). "The over-expression of DYRK1A is a suggested mechanism for inducing the neurofibrillary degeneration in Down syndrome individuals through tau hyperphoshorylation." (PMID 38932210, 2024). "DYRK1A plays a crucial role in neurogenesis, and dysregulation of DYRK1A results in severe neurodegenerative diseases such as Down syndrome or DYRK1A‐haploinsufficiency syndrome." (PMID 38723164, 2024). "Most recently, it has been reported that DYRK1A, which is triplicated in Down syndrome, can upregulate angiotensin-converting enzyme 2 (ACE2), the main receptor for SARS-CoV-2." (PMID 38540156, 2024). "Another triplicated gene in Down syndrome, DYRK1A, has recently been shown to upregulate the ACE2 receptor in human cells." (PMID 38540156, 2024). "A study emphasized the potential of DYRK1A inhibitors in enhancing cognitive functioning in mouse models with Down Syndrome." (PMID 39204195, 2024).
Down syndrome (continued). "DYRK1a is located on human chromosome 21, and, in trisomy, contributes to the neurological alterations observed in Down syndrome." (PMID 39305956, 2024). "The DYRK1A gene, which is considerably better characterized compared to DYRK1B, is significantly associated with the Down syndrome phenotype." (PMID 38932210, 2024). "A role of DYRK1A has also been suggested in other pathological conditions observed in Down syndrome patients, such as earlier onset of Alzheimer disease, type 2 diabetes, and craniofacial malformation." (PMID 37802655, 2023). "A previously uncharacterized protein, FAM53C, is identified as a binding partner for the kinase DYRK1A involved in numerous neurodevelopmental disorders, such as Down syndrome and autism spectrum disorder." (PMID 37802655, 2023). "This includes established connections such as DYRK1A in Trisomy 21/Down's syndrome and intellectual disability, and more novel identifications of SRPK signalling and mutations in intellectual disabilities." (PMID 37607329, 2023). "DYRK1A has been extensively studied because of its role in Down syndrome (DS), one of the most universally recognized genetic syndromes with estimated incidence of approximately 1 out of 1,100 live births." (PMID 37900285, 2023). "A polyphenolic green tea flavonol, epigallocatechin-3-gallate (EGCG), is a DYRK1A inhibitor that was shown to normalize DYRK1A activity in Down syndrome patients in a pilot study reversing cognitive deficits." (PMID 37568654, 2023). "Increased DYRK1A levels resulting from gene duplication, such as in Trisomy 21 or Down's Syndrome, are characterised by neurogenic and neurodevelopmental defects, congenital heart defects, leukaemia, and early onset neurodegenerative disease." (PMID 37607329, 2023). "DYRK1A is a ubiquitous enzyme that is overexpressed in Down syndrome patients through gene-dosage effects of trisomy chromosome 21." (PMID 36986543, 2023). "Triplication of DYRK1A gene is responsible for many pathological phenotypes observed in Down syndrome patients." (PMID 37802655, 2023). "Due to its location, triplication of the Dyrk1a locus in Down syndrome (DS) results in a 1.5-fold increase in Dyrk1a in the fetal and adult brain." (PMID 37469393, 2023). "However, since DYRK1A overexpression in Down’s Syndrome (DS) is strongly implicated in DS-associated oxidative stress, Alzheimer’s disease, and motor dysfunction, DYRK1A inhibitors may be beneficial in this condition, e.g., by upregulating the nuclear factor erythroid 2-like 2 (NRF2)." (PMID 36979889, 2023). "In Down syndrome (trisomy 21), DYRK1A is overexpressed 1.5-fold due to its position on chromosome 21, and dysregulation of DYRK1A dosage directly contributes to neurological defects and disease." (PMID 37310920, 2023). "The inhibition of DYRK1A is an enchanting therapeutic approach for the treatment of cognitive impairment in Down syndrome together with inhibiting tau hyperphosphorylation in Alzheimer’s disease." (PMID 37568654, 2023). "We investigated the effects of overexpression of Dyrk1A, an important factor contributing to some major Down syndrome phenotypes, on platelet number and bleeding in mice." (PMID 37415307, 2023). "Located on chromosome 21 in the Down syndrome critical region (21q22.22), DYRK1A is a highly dosage-sensitive gene." (PMID 37310920, 2023). "DYRK1A-dependent MAPT/Tau phosphorylation is one of the molecular bases for the early onset of Alzheimer disease in most Down syndrome patients, and DYRK1A inhibition is believed to be effective for treatment of Alzheimer disease." (PMID 37802655, 2023). "Decreased expression of DYRK1A has been found in patients with autism spectrum disorder (ASD), while elevated expression has been linked to Down syndrome (DS)." (PMID 36855151, 2023). "Further evidence supporting an important function for DYRK1A in the development of the central nervous system is discussed later via the role of DYRK1A in Trisomy 21/Down's syndrome." (PMID 37607329, 2023).
Down syndrome (continued). "We assessed DYRK1A in the plasma of cognitively healthy elderly volunteers, individuals with either Alzheimer’s disease (AD), tauopathies or Down syndrome (DS), and in lymphoblastoids from individuals with DS." (PMID 37015911, 2023). "The formation of NFTs in Down’s syndrome and other diseases is due to the overexpression of DYRK1A protein." (PMID 36741918, 2022). "Studies have shown that, in Down syndrome, when DYRK1A is overexpressed, it modulates the differentiation of neuronal cells, resulting in immature neurons via inhibiting the cell cycle." (PMID 35454940, 2022). "Selective inhibitors of DYRK1A have been extensively explored and are considered potential candidates for treating multiple diseases, including Down’s syndrome, Alzheimer’s disease, Parkinson’s disease and cancer." (PMID 35655269, 2022). "DYRK1A is a dual-specificity kinase that is overexpressed in Down syndrome (DS) and plays a key role in neurogenesis, neuronal differentiation and function, cognitive phenotypes, and aging." (PMID 36590914, 2022). "The inhibition of DYRK1A by ECGC has been examined in preclinical studies with the aim of improving cognitive functions in Down syndrome." (PMID 35596909, 2022). "In the same study, the authors showed that increased cardiac DYRK1A expression in Ts65Dn mice, a model of Down syndrome, delayed the exclusion of exon 5 during the neonatal period." (PMID 35596909, 2022). "DYRK1A inhibition has been shown to aid neuronal plasticity in patients suffering from Down syndrome, suggesting that this molecular pathway should be investigated in FASD disease." (PMID 36364431, 2022). "The DYRK1A gene is located within human chromosome 21q22.2, also known as the Down Syndrome Critical Region (DSCR)." (PMID 36012629, 2022). "In the context of NDD, Down’s Syndrome cells have increased expression of DYRK1A which leads to reduced NRSF/REST and misregulation of neurodevelopmental genes." (PMID 36216811, 2022). "Of note, increased DYRK1A expression in hearts from Ts65Dn mice, a mouse model of Down syndrome, impacts the splicing of TNNT2 and the relative proportions of cTnT transcript variants." (PMID 35596909, 2022). "DYRK1A is over-expressed in Down syndrome and is considered to be the major source of cognitive dysfunction in DS patients." (PMID 36364431, 2022). "EGCG was able to inhibit DYRK1A in the hippocampus and protect against cognitive deficits in mouse models of Down syndrome and humans by modulation of the Hcy level." (PMID 36394770, 2022). "The DYRK1A gene is located on chromosome 21; in Down’s syndrome, the protein expression is increased 1.5 fold." (PMID 36741918, 2022). "Dual-specificity tyrosine phosphorylation-regulated kinase 1A (DYRK1A) is a protein kinase that is abnormally expressed in many diseases such as Down syndrome or AD." (PMID 36615235, 2022). "The dual specificity tyrosine phosphorylation regulated kinase 1A (Dyrk1a) gene is located within the Down syndrome critical region of chromosome 21 and is a serine/threonine kinase that has been studied mostly in neuronal development and brain physiology." (PMID 34787650, 2022). "In Down syndrome, increased DYRK1A expression increases G1 cell cycle duration through phosphorylation and degradation of cyclin D1." (PMID 34708541, 2021). "It was subsequently found to also potently inhibit several members of the CLK and DYKRK families, including DYRK1A, and was able to block DYRK1A-related tau phosphorylation in a mouse model of Down Syndrome." (PMID 34445786, 2021). "There is also evidence that upregulation of DYRK1A leads to changes in neuronal proliferation in Down Syndrome." (PMID 34445786, 2021). "Further investigation has led to the discovery of the DYRK1A haploinsufficiency syndrome (also named Mental Retardation autosomal Dominant 7, MRD7)." (PMID 34828439, 2021).